DPPA5 (developmental pluripotency associated 5)
Description:
Involved in the maintenance of embryonic stem (ES) cell pluripotency. Dispensable for self-renewal of pluripotent ES cells and establishment of germ cells. Associates with specific target mRNAs (By similarity).
Synonyms: ESG1
Tractability: PROTAC: ubiquitination databases record sites on it.
Gene: Protein-coding gene on chromosome 6 (73,353,063 to 73,354,276, reverse strand). Ensembl gene ENSG00000203909.
Subcellular location: Cytoplasm
Subcellular location (Human Protein Atlas): Cell Junctions
Gene Ontology:
Molecular function: mRNA binding; RNA binding
Biological process: regulation of gene expression
Cellular component: cytoplasm
Genetic constraint (gnomAD): Loss-of-function variants: 13 observed, 13.88 expected, observed/expected ratio (o/e) 0.94, 90% interval 0.61 to 1.48. The upper end of that interval is the gene's LOEUF score, 1.48, which puts it in group 6 of 6, group 1 being the genes least tolerant of losing a copy. Missense variants: 132 observed, 162.96 expected, observed/expected ratio (o/e) 0.81, 90% interval 0.7 to 0.94. Synonymous variants: 53 observed, 62.82 expected, observed/expected ratio (o/e) 0.84, 90% interval 0.68 to 1.06.
Homologues: Orthologues: chimpanzee DPPA5 (100% identical), macaque DPPA5 (97% identical), rabbit DPPA5 (83% identical), dog DPPA5 (75% identical), pig DPPA5 (75% identical), rat Dppa5l1 (71% identical), mouse Dppa5a (64% identical). Paralogues in human: KHDC1L (23% identical), KHDC1 (21% identical).
Diseases named in the same sentence as DPPA5 in open-access papers:
DPPA5 is named in the same sentence as 5 diseases in open-access papers, as found by Europe PMC text mining. Sharing a sentence is not in itself a finding about the gene and the disease. The quoted sentences say what the papers report.
hyperlipidemia (1 paper, 2022). "In addition, significant upregulation was observed in DPPA5, DNM3OS, OR2T6, OR8H1 in four complications including neuropathy, ketoacidosis, hyperlipidemia and PCOs (p < 0.01) (Boxplots 8C, 8D, 8F,8H, respectively)." (PMID 36175575, 2022).
seminoma (1 paper, 2015). A radiosensitive malignant germ cell tumor found in the testis (especially undescended), and extragonadal sites (anterior mediastinum and pineal gland). "Furthermore, additional EC and pluripotency genes were upregulated (SOX2, LEFTY1 /2, DNMT3L, SALL4, DPPA5, BCAT1, FZD7, LIN28, ZIC3), while seminoma-associated genes where downregulated (SOX17, TFAP2C, cKIT, PRAME), without changing 5mC-levels." (PMID 26226633, 2015). "Among them, GDF3, NODAL, LEFTY1 /2, GAL, DPPA3, SOX2, DNMT3B /L, DPPA5, BCAT1, FGF2, PRDM14, ZIC3 and FZD7, while seminoma markers SOX17, cKIT and PRAME were downregulated." (PMID 26226633, 2015).
cancer (1 paper, 2007). A tumor composed of atypical neoplastic, often pleomorphic cells that invade other tissues. "As in the cancer cell lines, we observed promoter hypomethylation in the primary tumors; the frequency of hypomethylation was 5% (1/20) for ANKRD30A, 20% (4/20) for FLJ40201, 0% (0/20) for INSL6, 30% (6/20) for SOHLH2, 20% (4/20) for FTMT, 25% (5/20) for C12orf12, and 30% (6/20) for DPPA5." (PMID 17967063, 2007).
tumor (1 paper, 2010). "Ecat1, Dppa5, and GDF3 genes are expressed in ES cells, but their expression in tumor has not yet been reported." (PMID 20950440, 2010).
DPPA5 also shares sentences with these, for which no sentence is quoted: neuropathy (1 paper).